PIK3CA (phosphatidylinositol-4,5-bisphosphate 3-kinase catalytic subunit alpha)
Diseases named in the same sentence as PIK3CA in open-access papers (continued):
Sharing a sentence is not in itself a finding about the gene and the disease.
breast tumors (158 papers, 2005 to 2026). "Of the 14 primary breast tumors presenting with PIK3CA mutations distant metastases were diagnosed in 10/14 cases whereas in wild type tumors, this ratio was 11/20." (PMID 39929942, 2025). "A tumor-initiating role for the PIK3CA (H1047R) variant has been demonstrated in mouse breast tumor models, and functionally, this mutation has been shown to increase PI3K enzyme activity in vivo." (PMID 39462049, 2024). "By further exploring the more recent molecular insights, it has been reported that breast NECs harbor PIK3CA mutations in a varying percentage (7%–33%), which is less frequent than the other more common breast tumor types." (PMID 39021492, 2024). "On the other hand, alpelisib selectively inhibits the growth of ER+ breast tumors harboring PIK3CA mutations making it an ideal agent for PIK3CA mutated breast tumors when compared to everolimus." (PMID 38003387, 2023). "Approximately 30–40% of all ER+ breast tumors exhibit an activating mutation of PIK3CA, which can either increase the catalytic activity or cause the retention of the p110α subunit, thereby promoting excessive cell multiplication and resistance to apoptosis." (PMID 36901954, 2023). "Significant associations of PIK3CA mutations to lower grade and smaller size of breast tumors were also reported in a meta-analysis containing 19 individual studies." (PMID 37454130, 2023). "PI3K/AKT signaling system is substantially active in carcinogenesis; PIK3CA, PIK3R1, PTEN, AKT, and other genes have high-frequency mutations (PIK3CA gene is mutated in around 36% of breast tumors)." (PMID 36937843, 2023). "Breast tumors harboring a PIK3CA-mutation were large and exhibited liquefied necrosis and posterior echo attenuation in the nodule." (PMID 38025526, 2023). "A tumor initiating role for the p.PIK3CA H1047R variant has been demonstrated in mouse breast tumor models and functionally the mutation has been shown to increase the PIK3CA enzyme activity in vivo." (PMID 36635367, 2023). "This is, to the best of our knowledge, the first meta-analysis providing data on the discordance rates of PIK3CA-mutations between primary breast tumors and their matched metastases." (PMID 37392328, 2023). "In total, 13 out of 23 PIK3CA double mutations are harbored by at least one breast tumor and there are 215 double mutant tumors." (PMID 36808143, 2023). "The detected variants were located in the known PIK3CA hotspot regions, reported in breast tumors in the COSMIC database and functionally confirmed to affect PIK3CA function." (PMID 35768433, 2022). "Activating PIK3CA point variants are the most prevalent in breast tumors and were confirmed to lead to malignant transformation." (PMID 35768433, 2022). "We found a frequent allelic expression imbalance between the missense mutant and wild-type PIK3CA alleles in breast tumors from the METABRIC (70.2%) and the TCGA (60.1%) projects." (PMID 35676284, 2022). "Mutant DNA and mRNA are secreted by breast tumour cells via sEVs and can be integrated into heterologous cells by sEVs; for example, phosphoinositide 3-kinase alpha (PIK3CA) mutation has been demonstrated." (PMID 36096820, 2022).
breast tumors (continued). "To test this, we carried mutant vs. wild-type allelic expression analysis in breast tumor samples carrying somatic PIK3CA missense mutations on two independent sets of data, the METABRIC (n = 94) and the TCGA (n = 178) projects." (PMID 35676284, 2022). "In the METABRIC and TCGA datasets, a vast majority of breast tumors (88% to 96%) with multiple PIK3CA mutations also had double mutations." (PMID 34093841, 2021). "These analyses resulted in the identification of 62 different phosphosites in PIK3CA mutated breast tumors, including RPS6KA5 and EIF2AK4, explaining the activation of the pathway and revealing possible druggable kinases in this pathway." (PMID 33669749, 2021). "A PI3Kα-selective inhibitor has recently been approved for use in breast tumors harboring mutations in PIK3CA, the gene encoding p110α." (PMID 34762647, 2021). "The patient’s breast tumour carried a PIK3CA mutation (also found in the PDX) and the patient was treated with a PI3Kα inhibitor combined with the AI letrozole in the neo-adjuvant setting." (PMID 32792481, 2020). "An increase in PIK3CA mutations have been observed in relapsed breast tumors as compared to primary breast tumors." (PMID 32695676, 2020). "Data obtained using the sensitive and quantitative ACB-PCR approach generated a number of interesting findings and expanded current knowledge regarding PIK3CA mutation in human breast tumors." (PMID 30813596, 2019). "Further, compensatory ERK activation was observed in vivo in a genetically modified mouse model of HER2+ breast tumour with co-existing PIK3CA (H1047R) mutation following inactivation of the oncogenic PI3K." (PMID 35582276, 2019). "Breast tumors with mutated PIK3CA were more likely to be ER positive (P < 0.001) and PR positive (P < 0.001)." (PMID 29636477, 2018). "The PTEN/PI3K pathway is relevant in BC because PTEN loss and PIK3CA mutations have been found in around 30 and 40% of primary breast tumors, respectively." (PMID 30294328, 2018). "In contrast, our findings suggest an underlying regulating mechanism through PDGF-D and FLT1, driven by PIK3CA mutation in breast tumors." (PMID 28392480, 2017). "After targeted NGS analysis revealed the same PIK3CA mutation in both the breast and lung tumours there was a total agreement among the pathologists that the breast tumour was a malignant adenomyoepithelioma with metastases to the lung." (PMID 28347348, 2017). "For example, ZSTK474 inhibitor displayed a potent anticancer activity in human tumor xenografts while BYL719 has shown synergistic antineoplastic efficacy when used in endocrine cure against ER+/PIK3CA mutated breast tumor cells." (PMID 28390196, 2017). "In human patients, PIK3CA mutant breast tumors acquire mutations in Pten following treatment with BEZ235 in the clinic, which likely further activates AKT." (PMID 28445155, 2017). "This provides a rationale for the combined targeting of p110α with IGF1R or p110β in patients with breast tumors harboring PIK3CA mutations." (PMID 27048245, 2016). "In general, they found that patients with breast tumors displaying a PIK3CA mutation-like expression pattern exhibited poor survival." (PMID 27589846, 2016). "PIK3CA mutation is found to be commonly associated with most breast tumors, including luminal-like, ErbB2-over-expressing and basal-like subtype." (PMID 27941987, 2016). "To this end, we compared the performance of NGS and SGS in the same cohort of patients, and identified PIK3CA mutations in 34.4 % of breast tumors using NGS, which is in agreement with the mutation rate reported in TCGA." (PMID 26587011, 2015).
breast tumors (continued). "Since PIK3CA mutations occur in about a third of HER2 amplified breast tumors, it is important to understand the impact of these mutations on response to combinations of drugs that target HER2 and AKT." (PMID 26181325, 2015). "Further studies are needed to systematically explore the functional relevance of PIK3CA mutations and the contribution of PIK3CA mediated activation of the downstream and upstream signaling pathways in breast tumor development and progression." (PMID 26587011, 2015). "A recent report from TCGA identified a hypermethylated, HR+ breast tumor subset with lower Wnt-pathway gene expression and fewer PIK3CA and MAP3K1 mutations." (PMID 25287138, 2014). "The results of this presurgical study of 85 breast tumours treated with 2 weeks of anastrozole confirm the high prevalence of PIK3CA mutations and their relationship with markers of good clinical prognosis in ER + disease." (PMID 24981670, 2014). "PTEN loss occurring in up to 30% of unselected breast tumor cohorts is also predominantly mutually exclusive with PIK3CA and AKT1 mutations." (PMID 24229379, 2013). "Researchers from the Tamoxifen Exemestane Adjuvant Multinational (TEAM) trial reported sequencing of the gene PIK3CA, which encodes the protein phosphatidylinositol 3-kinase, in oestrogen receptor positive breast tumours." (PMID 23441137, 2013). "We have described a novel mouse model that accurately reproduces the scenario of a somatic mutation in a single PIK3CA allele as occurs in human breast tumors." (PMID 22666336, 2012). "In breast tumours, PIK3CA mutations have been consistently associated with ER-positive and human epidermal growth factor receptor-2 (HER2)-positive tumour status." (PMID 22033276, 2011). "Among them, activating PIK3CA mutations have been identified in about 15% to 30% of breast tumors and are more commonly associated with ER+ disease." (PMID 22132754, 2011). "For example, amplification of HER2 and mutational activation of PIK3CA or PTEN inactivation occur together in many breast tumors." (PMID 21646685, 2011). "CYP4Z2P is located in a head-to-head orientation close to CYP4Z1 in chromosome region 1p33, raising the possibility that expression of these two genes is co-regulated in PIK3CA-mutated breast tumors." (PMID 21209903, 2010). "We used a two-step strategy to identify downstream target genes and signaling pathways affected by PIK3CA mutations in breast tumors." (PMID 21209903, 2010). "This PIK3CA mutation frequency of 37% was in keeping with the results of previous studies showing a mutation rate of up to 40% in ERα-positive breast tumors." (PMID 21209903, 2010). "PAM prediction analysis was then used to test the ability of each gene to classify the 249 ERα-positive breast tumors according to PIK3CA mutation status." (PMID 21209903, 2010). "Here, we compared gene expression in PIK3CA-mutated and PIK3CA wild-type ERα-positive breast tumors, using a genome-wide microarray and subsequently real-time quantitative reverse transcriptase-polymerase chain reaction (RT-PCR)." (PMID 21209903, 2010). "We identified a 20.6% (19 of 92) and 33.3% (5 of 15) PIK3CA somatic mutation frequency in primary breast tumors and cell lines, respectively." (PMID 16168105, 2005). "Notably, in primary and metastatic ER + /HER2-positive breast tumors, the incidence of PIK3CA mutations is 40%, highlighting its crucial role in this subtype." (PMID 40050490, 2025). "This reflects the fact that a substantial proportion of the alterations were considered potentially actionable based on data from randomized trials in other tumor types, case reports, or preclinical studies (e.g., PIK3CA mutations in non‐breast tumors—Tier IIC)." (PMID 40755376, 2025). "Therefore, combination therapy of PI3K inhibitors and fulvestrant offers a promising therapeutic approach for AI-resistant breast tumors with PIK3CA mutations." (PMID 40303296, 2025).
breast tumors (continued). "In BC, the most frequent PIK3CA mutations lead to protein residue changes at the following positions of exon mutations: E542K, E545K in exon 9 and H1047R in exon 20, comprising approximately 78% of all PIK3CA mutations observed in breast tumors." (PMID 38344201, 2024). "The breast tumors of patients with mutated PIK3CA were large and exhibited liquefied necrosis." (PMID 38025526, 2023). "Interestingly, the PIK3CA mutation combines with another gene mutation in immune-related breast tumors." (PMID 38017109, 2023). "A systematic literature search was performed in three different databases (Embase, Pubmed, Web of Science) and—upon screening—a total of 25 studies reporting PIK3CA mutational status both on primary breast tumors and their matched metastases were included in this meta-analysis." (PMID 37392328, 2023). "PIK3CA mutated breast tumors were predicted to be more sensitive to Alpelisib." (PMID 34548481, 2021). "Finally, the frequency of the top mutated cancer driver genes (>5%) in HM breast tumors varies among the evaluated ancestries, with PIK3CA, MAP3K1 and PTEN having the highest similarities." (PMID 33854067, 2021). "Importantly, the correlation of a high PI3K signaling score with ER-negativity contrasts with the known enrichment of PIK3CA mutations in ER-positive breast tumors, which were also reproduced by our analyses." (PMID 34762647, 2021). "This suggests that while PI3Kα inhibition may be optimally tailored toward PIK3CA-mutated breast tumor types, PI3Kβ inhibition may be exploited for PTEN-deficient breast tumors, notably for TNBC." (PMID 34026830, 2021). "In addition, PIK3CA mutations were more likely to be observed among patients with HER2-positve breast tumors who have liver metastases." (PMID 32695676, 2020). "Interestingly, while 80% of EBVaGC tumors display an activating mutation in PIK3CA, high CIMP breast tumors are strongly enriched for low mutation rates of PIK3CA, MAP2K4, and MAP3K1." (PMID 33126718, 2020). "HER2-overexpressing breast tumors were correlated with a high PIK3CA mutation rate." (PMID 31404155, 2019). "In HER2+ breast tumors, PIK3CA mutation (H1047R, E545K, or both) was found in 63% of tumors, which may subvert the efficacy of HER2-targeted therapies and ultimately result in relapse." (PMID 30813596, 2019). "Moreover, JNK signaling is also inhibited by phosphorylation of MAP2K4 by AKT in breast tumors with AKT activation caused by ‘driver’ mutations in PTEN or PIK3CA." (PMID 29856313, 2018). "However, results were inconsistent in ER+/HER2-breast tumors where they found that a PIK3CA mutant gene signature was associated with improved survival." (PMID 27589846, 2016). "Canonical PIK3CA mutations were seen in the radiation-associated breast tumours." (PMID 27615322, 2016). "Therefore, two breast tumors with mutation and amplification respectively in the same gene, such as in PIK3CA or GATA3, yield two distinct tumors of low and high grade, respectively." (PMID 27283966, 2016). "As PIK3CA mutations are reported in 10-40% of BCs we hypothesized that mutated-PIK3CA breast tumor expressing COX-2 could benefit from treatment with a COX-2 inhibitor such as celecoxib." (PMID 27835884, 2016). "Interesting a high frequency of PIK3CA mutations (28%) was observed in HER2+ breast tumors." (PMID 25051360, 2014). "The paradigm in this work exemplified by combining PIK3CA mutations with response to PI3K inhibitors could be extended to other breast tumor subtypes and driver oncogenes." (PMID 25032256, 2014).
breast tumors (continued). "This study of 452 breast tumors confirms the high prevalence (33.4%) of PIK3CA mutations." (PMID 22330809, 2012). "For example, mutant alleles of PIK3CA were identified in approximately 30% of breast tumors." (PMID 21646685, 2011). "Finally, PIK3CA mutations are found in many papillary breast tumors and in androgen receptor positive apocrine breast tumors, as well as in premalignant lesions such as DCIS." (PMID 21646685, 2011). "Somatic mutations in phosphoinositide-3-kinase catalytic subunit alpha (PIK3CA) are frequent in breast tumours and have been associated with oestrogen receptor (ER) expression, human epidermal growth factor receptor-2 overexpression, lymph node metastasis and poor survival." (PMID 22033276, 2011). "The pathological role of these gain-of-function PIK3CA mutations in breast tumors, and particularly in ERα-positive breast tumors, is largely unknown." (PMID 21209903, 2010). "Thirty-eight of these 39 unique genes were over-expressed in ERα-positive breast tumors with PIK3CA mutations, 16 being up-regulated at least 3-fold, while only one gene (NKAIN1, encoding Na+/K+ ATPase interacting protein) was down-regulated, with a FC of 3.52." (PMID 21209903, 2010). "Selected categories significantly over-represented in PIK3CA-mutated breast tumors." (PMID 21209903, 2010). "PIK3CA mutations have been observed in 30% to 40% of ERα-positive breast tumors." (PMID 21209903, 2010). "Moreover, PIK3CA mutations appear in breast tumors associated with PTEN loss or HER overexpression." (PMID 33375317, 2020). "PIK3CA mutations may provide an opportunity to develop novel drugs that target altered PIK3CA, or combination therapy based on the current regimen, which may yield the maximum effect on breast tumors." (PMID 31404155, 2019). "Thus, Wnt pathway activation appears to be an important consequence of PIK3CA mutations in breast tumors, in keeping with recently observed crosstalk between the PI3K/Akt and Wnt pathways in both physiological (myeloid progenitor cells) and pathological conditions (medulloblastoma)." (PMID 21209903, 2010). "Inhibition of cPLA2 by small-molecule ASB14780 downregulated the generation of arachidonic acid and, in combination with dietary fat restriction, resulted in growth inhibition of mutant PIK3CA-bearing breast tumors." (PMID 40427519, 2025). "Concordantly, the FAKTION trial showed that PIK3CA-mutant ER+ metastatic breast tumors benefit from combined capivasertib and fulvestrant." (PMID 36901954, 2023). "We detected four hotspot PIK3CA somatic variants in the uninvolved mammary gland, all of them have been described in the COSMIC database and reported in breast tumors." (PMID 35768433, 2022). "Activation of PIK3CA leads to formation of breast tumours with immune cell infiltration, as well as gene expression linked to Treg cell signalling and activation of targetable immune checkpoint pathways." (PMID 35043008, 2022).